CTLA4 (cytotoxic T-lymphocyte associated protein 4)
Diseases named in the same sentence as CTLA4 in open-access papers (continued):
Sharing a sentence is not in itself a finding about the gene and the disease.
rheumatoid arthritis (167 papers, 2007 to 2025). A chronic, systemic autoimmune disorder characterized by inflammation in the synovial membranes and articular surfaces. "Although CTLA4 is expressed on CD4+ T cells, the association of rheumatoid arthritis with the polygenic score for CD4+ T cell count was much weaker than the association with the GATE score for CTLA4." (PMID 39887658, 2025). "Abatacept, a co-stimulatory blocker comprising the extracellular portion of human CTLA-4 linked to the Fc region of IgG1, is approved for the treatment of rheumatoid arthritis." (PMID 38567291, 2024). "Abatacept, a medication previously approved by the FDA for rheumatoid arthritis, has demonstrated powerful clinical response in CTLA4-deficient patients." (PMID 33442967, 2021). "An analogous situation has been reported in Tregs from rheumatoid arthritis patients, which secreted low levels of regulatory cytokines and had defects in the expression of CTLA-4, associated with increased bone destruction." (PMID 33149125, 2020). "Like for other immune checkpoint markers PD-1 and CTLA-4, there is a polymorphism of the btla gene that results in less inhibition, and that is associated with rheumatoid arthritis." (PMID 32197584, 2020). "A well-established rheumatoid arthritis susceptibility variant near CTLA4 decreases CTLA4 levels in T cells; here, we identify how this reduced immune checkpoint function is associated with increased levels of IL-2-producing CD8+ T cells." (PMID 30332657, 2018). "The polymorphism of CTLA-4 had been suggested in many diseases which included Addison's disease, autoimmune hypothyroidism, and rheumatoid arthritis." (PMID 25121088, 2014). "Recently, a number of studies have been performed to explore the association between CTLA-4 A49G polymorphism and rheumatoid arthritis (RA)." (PMID 25128482, 2014). "In this Hungarian cohort, we chose to evaluate the allele and genotype distribution of two variants of the CTLA4 gene, in relation to the development of rheumatoid arthritis." (PMID 21157511, 2010). "CTLA4 polymorphisms demonstrate significant pleiotropic effects, showing associations with multiple immune-mediated pathologies including systemic lupus erythematosus, rheumatoid arthritis, autoimmune diabetes, and allograft rejection episodes." (PMID 41000380, 2025). "Here, we describe a family with autoimmune phenotypes (Hashimoto thyroiditis, psoriasiform dermatitis, celiac disease/inflammatory bowel disease, and rheumatoid arthritis), segregating across three different generations due to a recurrent missense variant [c.436G>A, p.(Gly146Arg)] in the CTLA4 gene." (PMID 40149457, 2025). "Notably, seven regions outside the HLA region that contain SNPs associated with rheumatoid arthritis are trans‐eQTLs for CTLA4." (PMID 39887658, 2025). "Furthermore, links between CTLA4 gene polymorphisms and rheumatoid arthritis, T1D, systemic lupus erythematosus (SLE), and multiple sclerosis have been found, pointing to a shared genetic vulnerability for autoimmune etiology." (PMID 39854591, 2025). "Cytotoxic T lymphocyte-associated protein 4 (CTLA-4) gene polymorphisms may be involved in the risk of Rheumatoid arthritis (RA)." (PMID 34339393, 2021). "PTPN22, PADI-4, and CTLA-4 have been associated with risk for rheumatoid arthritis (RA)." (PMID 18462498, 2008). "For three of these genes—CD5, CTLA4, and SLAMF1—associations of rheumatoid arthritis with SNPs within 200 kb of the transcription site are listed in the GWAS catalog." (PMID 39887658, 2025). "Abatacept, a fusion protein combining cytotoxic T-lymphocyte-associated protein 4 (CTLA-4) with the Fc portion of IgG1, modulates CD80/CD86:CD28 signaling and is approved for rheumatoid arthritis." (PMID 40869539, 2025).
rheumatoid arthritis (continued). "For example, in rheumatoid arthritis and skin cancer our genetic analysis highlighted CTLA4, a shared target for medications across both conditions." (PMID 39919332, 2025). "Abatacept is a biologic drug that contains a CTLA-4 mimic currently approved for rheumatoid arthritis and has also been tested for T1D." (PMID 41299435, 2025). "Numerous previous studies have established the connection between CTLA-4 and autoimmune thyroiditis, Graves' disease, myocarditis, pancreatitis, multiple sclerosis, rheumatoid arthritis, and type I diabetes." (PMID 40392591, 2025). "Changes after treatment with different biological disease-modifying antirheumatic drugs, including Ig-CTLA4, were also observed in rheumatoid arthritis." (PMID 39001488, 2024). "Fine-mapping and functional studies implicate rs117701653, a non-coding single nucleotide polymorphism in the CD28/CTLA4/ICOS locus, as a risk variant for rheumatoid arthritis and type 1 diabetes." (PMID 38459032, 2024). "CTLA4Ig is a dimeric fusion protein of the extracellular domain of cytotoxic T-lymphocyte protein 4 (CTLA4) and an Fc (Ig) fragment of human IgG1 that is approved for treating rheumatoid arthritis." (PMID 36797799, 2023). "Abatacept (CTLA4-Ig)—a monoclonal antibody which restricts T cell activation—is an effective treatment for rheumatoid arthritis (RA)." (PMID 38132128, 2023). "These medications are employed in clinical settings to manage autoimmune diseases like psoriasis and rheumatoid arthritis (RA), wherein genetic abnormalities or modified posttranslational variations of the CTLA-4 gene or its promoter are detected." (PMID 37828948, 2023). "CTLA-4 has been reported to be hypermethylated at the specific positions on Tregs of rheumatoid arthritis patients, such that the CTLA-4 expression is down-regulated." (PMID 37954599, 2023). "T cell-targeted biologics such as abatacept also known as CTLA-4 Ig was proven to be efficient in inflammatory diseases such as psoriasis and rheumatoid arthritis (RA)." (PMID 35769669, 2022). "We further show that administration of abatacept (Orencia), an FDA-approved drug for rheumatoid arthritis consisting of the extracellular domain of CTLA-4 fused to human Fc, abrogates these effects by inhibiting B7-1:p75NTR binding." (PMID 36107635, 2022). "This is supported by existing therapies in which a CTLA4 fusion protein is administered to patients with rheumatoid arthritis to help reduce inflammation." (PMID 35618845, 2022). "In these studies, the immunosuppressive potential of sCTLA-4 approached that of CTLA4-Ig, the dimeric fusion protein, which has proven clinically useful for the treatment of rheumatoid arthritis." (PMID 35069536, 2021). "Two CTLA4-Ig drugs on the market, abatacept and belatacept, are clinically approved for treatment of rheumatoid arthritis and prophylaxis of renal transplant rejection, respectively." (PMID 34141826, 2021). "CTLA-4 signaling has been shown to be involved in the pathogenesis of many AIDs including rheumatoid arthritis (RA), systemic lupus erythematosus (SLE), multiple sclerosis (MS), and type-1 diabetes (T1D)." (PMID 33692958, 2021). "Logistic regression analysis of association between CTLA-4 rs231775, CTLA-4 rs16840252 and CD86 rs17281995 polymorphisms and the risk of rheumatoid arthritis." (PMID 33604347, 2021). "The introduction of the CTLA-4 recombinant fusion protein has demonstrated therapeutic effects by selectively modulating T-cell activation in rheumatoid arthritis." (PMID 33504785, 2021). "Recombinant CTLA4-Ig has been developed and approved for rheumatoid arthritis and focal segmental glomerulosclerosis (FSGS) with CD80+ podocytes." (PMID 32512831, 2020). "Since cytotoxic T-lymphocyte-associated protein 4 (CTLA4) competes with CD28 for binding to CD80/86, biological therapies based on CTLA4 are approved for rheumatoid arthritis and kidney transplantation." (PMID 32849502, 2020).
rheumatoid arthritis (continued). "For instance, abatacept (CTLA-4-Ig) is effective in alleviating disease activity in rheumatoid arthritis (RA) patients who have an inadequate response to methotrexate or anti-tumor necrosis factor (TNF)-α therapies." (PMID 32228715, 2020). "We initially modulated CD28 costimulation by titrating abatacept (CTLA4-Ig), a drug used in treating immune diseases (e.g. rheumatoid arthritis) that reduces T-cell activation by blocking costimulation." (PMID 33223527, 2020). "Examples include abatacept (CTLA4-Fc) in treating rheumatoid arthritis, psoriatic arthritis and juvenile idiopathic arthritis and belatacept (an engineered version of CTLA4-Fc) in preventing transplant rejection." (PMID 32038630, 2019). "These two immunosuppressive drugs are both CTLA4-Fc fusion proteins used in treatment of rheumatoid arthritis (abatacept) or kidney transplantation (belatacept)." (PMID 30918073, 2019). "The PD-1/PD-L1 immune checkpoint blockage in cancer therapy, the interfering CD28 and CD80/CD86 binding with CTLA-4-Ig in the treatment of rheumatoid arthritis and using anti-CTLA-4 monoclonal antibody (mAb) for cancer treatment are the best examples." (PMID 31120992, 2019). "Genes involved in regulating peripheral tolerance were found have effects on the development of RA, such as PTPN22 C1858T (rs2476601), CTLA-4 A49G, and PDCD-1 (rs36084323), and PD-L1 6777G was associated with the prevalence of rheumatoid nodules." (PMID 28969061, 2017). "CTLA4-Ig is currently approved for the treatment of rheumatoid arthritis, but in SLE its benefits have been more difficult to establish, even though its immunosuppressive effects were first clearly established in lupus mouse models." (PMID 27487771, 2016). "Several clinical trials have also demonstrated CTLA-4-Ig (abatacept) to be effective in the treatment of rheumatoid arthritis; however, a significant proportion of patients displays a limited clinical response." (PMID 26276872, 2015). "It is believed to be effective in the treatment of rheumatoid arthritis by inhibiting costimulation of T cells via blocking CD28–B7 interactions as CTLA-4 binds to both B7.1 (CD80) and B7.2 (CD86)." (PMID 26290328, 2015). "The development of IBD has also been reported in a patient treated with CTLA-4 Ig for rheumatoid arthritis." (PMID 26322044, 2015). "CTLA4-Ig has proved effective both in experimental models and in the clinic with psoriasis and rheumatoid arthritis." (PMID 26322044, 2015). "As previously discussed, CTLA-4 Ig is already an approved clinical therapy for the treatment of rheumatoid arthritis." (PMID 23844072, 2013). "Currently, a recombinant fusion protein of CTLA4-immunoglobulin (CTLA4-Ig, Abatacept, Orencia) is licensed in the United States for the treatment of rheumatoid arthritis." (PMID 22369699, 2012). "CTLA4 participates in the pathways of autoimmune thyroid disease, CAMs, and the T-cell receptor signaling and rheumatoid arthritis pathways." (PMID 22536280, 2012). "For five of the 16 putative core genes—CD5, CTLA4, SLAMF1, PDCD1, and TNFRSF14—that were identified through association of GATE scores with rheumatoid arthritis, associations of rheumatoid arthritis with SNPs within 200 kb of the transcription site are listed in the GWAS catalog." (PMID 39887658, 2025). "Indeed, human CTLA-4 Ig (abatacept) has been approved for treating adult rheumatoid arthritis and juvenile idiopathic arthritis." (PMID 40463388, 2025). "Nevertheless, there is evidence that CTLA4-Ig are affecting macrophages, which was already shown for abatacept, a first-generation CTLA4-Ig that is frequently used in the treatment of patients with rheumatoid arthritis." (PMID 37175964, 2023). "In humans, CTLA4 and PD-1 polymorphisms were associated with various ADs, including Grave’s disease, autoimmune hypothyroidism, systemic lupus erythematosus, mild glomerulonephritis, cardiomyopathy, ankylosing spondylitis, rheumatoid arthritis (RA), type 1 diabetes, and CD." (PMID 35327411, 2022).
rheumatoid arthritis (continued). "In patients with Rheumatoid Arthritis (RA), the abatacept treatment leads to reduced plasmablast counts, decreased frequency of self-reactive memory B cells and curtailed serum lgG, suggesting that CTLA-4 help Tregs repress B cells." (PMID 36211467, 2022). "Furthermore, studies utilizing CTLA-4-Ig (abatacept) to treat type 1 diabetes and rheumatoid arthritis have shown a reduction in the frequency of CD4+ Tregs in these patients." (PMID 36761170, 2022). "The rs3087243 in CTLA4 gene was not confirmed to be in association with rheumatoid arthritis in bivariate and multivariate risk models." (PMID 33059697, 2020). "It has been shown that CTLA-4 promoter methylation involved the pathology of rheumatoid arthritis." (PMID 32148437, 2020). "Vice versa, the administration of CTLA-4-Ig (belatacept or abatacept) exerts beneficial effects on a range of autoimmune disorders such as airway inflammation, rheumatoid arthritis, and dermal fibrosis or to prevent rejection of allografts, particularly renal transplants." (PMID 31950032, 2019). "For example, signaling through CTLA4 induces an anergic state in naïve T-cells, and therefore Abatacept, a fusion protein composed of the Fc portion of human IgG1 fused to the extracellular domain of the CTLA4, is used for treatment of rheumatoid arthritis." (PMID 31561568, 2019). "Moreover, in patients with rheumatoid arthritis and following kidney transplantation, treatment with CTLA4-Ig has been shown to decrease the incidence of circulating Treg." (PMID 29520267, 2018). "These include alefacept, a recombinant human fusion protein consisting of leukocyte-function-associated antigen (LFA) type 3 and IgG1 (approved for the treatment of psoriasis in 2003); and abatacept, a CTLA4-IgG fusion protein approved for the treatment of rheumatoid arthritis." (PMID 28723914, 2017). "Previous work suggested that treatment with CTLA4-Ig (abatacept), a molecule that binds and blocks B7-1 and is licensed for the treatment of rheumatoid arthritis, could ameliorate DN." (PMID 27055155, 2016). "However, patient responses to CD28-ligand blockade by abatacept (CTLA-4-Ig) in conditions such as rheumatoid arthritis are variable and often suboptimal." (PMID 26276872, 2015). "Abatacept is a CTLA-4-Ig that is highly glycosylated and has therapeutic functions on rheumatoid arthritis (RA)." (PMID 39062019, 2024). "However, in regard to immunosuppression, CTLA-4 fusion proteins are clinically approved for use in rheumatoid arthritis and kidney transplantation, and a potentially novel PD-1 agonist is being tested in humans in a phase 1 trial (ClinicalTrials.gov identifier NCT03337022)." (PMID 34752418, 2021). "Recombinant soluble cytotoxic T lymphocyte antigen-4 (CTLA-4-Fc) is clinically effective for suppressing T cell activation in autoimmune diseases such as rheumatoid arthritis (RA)." (PMID 33926067, 2021). "Abatacept (CTLA4-Ig) has been approved by the FDA for use in rheumatoid arthritis (RA) patients with an inadequate response to one or more of the disease-modifying antirheumatic drugs." (PMID 29123529, 2017). "Moreover, treatment with CTLA4-Ig (abatacept), a molecule that binds B7-1 (and, with lower avidity, B7.2), blocks B7-1 on podocytes and is licensed for the treatment of rheumatoid arthritis, reduces urinary albumin excretion and improves kidney pathology in two animal models of DN." (PMID 27055155, 2016). "Thus, if the CTLA-4 blockade enhances the intratumoral T-effector/T-regulator cell ratio in cancer patients, by depleting T-regulator cells, immunotherapy modulating CTLA-4 (such as abatacept) improves the regulatory T-cell inhibitory function in rheumatoid arthritis patients." (PMID 26337719, 2015). "Indeed, several studies reported an overall decrease in peripheral Tregs in kidney transplant recipients or rheumatoid arthritis patients treated with Nulojix® or Orencia®, which are CTLA4-Ig molecules binding CD80/86 and preventing CD28-mediated costimulation." (PMID 24376655, 2013).